TGFBR3 (transforming growth factor beta receptor 3)
Diseases named in the same sentence as TGFBR3 in open-access papers (continued):
Sharing a sentence is not in itself a finding about the gene and the disease.
tumor (continued). "Several studies have shown that TGFBR3 is a tumor suppressor gene that inhibits the proliferation or induces the apoptosis of cancer cells, but other studies have also found that TGFBR3 may promote proliferation in some circumstances." (PMID 41444423, 2025). "Additionally, TGFBR3 appears to influence the activity of CAFs, further shaping tumour–stroma interactions." (PMID 41463344, 2025). "We identified CD36, MMP1, TGFBR3, TWIST2, ITGB1, and FGF19 as associated with poorer outcomes: CD36 enhances tumour stemness and growth, MMP1 facilitates metastasis, TGFBR3 and TWIST2 promote EMT and invasion, ITGB1 supports cell adhesion and survival, and FGF19 drives proliferation." (PMID 41007296, 2025). "The effect of TGFBR3 on various tumors and its influence on tumor progression is multifaceted." (PMID 39404708, 2024). "TGFBR3 has been identified as a tumor suppressor in a variety of cancers." (PMID 39404708, 2024). "Notably, they also found that miR-424 and TGFBR3 expression correlated with the degree of tumour differentiation, depth of tumour infiltration, TNM stage, vascular infiltration, lymphatic node metastasis (LNM), and distant metastasis in CRC patients." (PMID 36338118, 2022). "Furthermore, we found that dormant residual tumor cells in vivo exhibit increased expression of Tgfbr3 (TGFβR-III), as well as its ligand Tgfb2 (TGFβ-II), and markedly decreased expression of Plaur (uPar) compared to both primary and recurrent tumor cells." (PMID 34088357, 2021). "TGFBR3 can act as a tumor suppressor to hinder tumor progression." (PMID 34266418, 2021). "In our study, we found hundreds of genes with a difference in expression by more than twofold after HELLS knockdown in the three PC cell lines; among them, 23 genes differed among the cell lines, including several tumor suppressor genes, such as TGFBR3, BTG2, and DKK1." (PMID 33280236, 2021). "Regarding the female dogs, we sequenced 79 BC-related genes, and those with high number of variants shared by tumor fragments and plasma were GATA3 and mTOR (missense), SFRP1 (frameshift insertion), BRCA2 (multi hit), FOXC2, ATM, TGFBR3, and BRIP1 (missense and multi hit mutations)." (PMID 34680380, 2021). "Moreover, the expression of TGFBR3 was downregulated in the blood and tumor tissue cells of patients with stage I LUAD." (PMID 34036102, 2021). "Thus, our data provide evidence that HELLS can serve as a potential oncogene and suitable biomarker to evaluate chemotherapy sensitivity via epigenetically silencing the tumor suppressor TGFBR3 in PC." (PMID 33280236, 2021). "Similarly, we observed a significant reduction in TGFBR3 mRNA expression in tumor tissues compared to the healthy tissues." (PMID 32471132, 2020). "To test whether TGFBR3 overexpression affects tumor metastasis, we injected the mice intrabuccally with vector- or TGFBR3-expressing OC-2 cells." (PMID 32471132, 2020). "The expression of TGFB1 is increased in tumor cells compared with normal thyroid tissue, and it could be accepted by transforming growth factor beta receptor TGFBR3, which is a tumor suppressor protein." (PMID 31126066, 2019). "Moreover, xenograft experiments showed that overexpression of let‐7a or knockdown of TGFBR3 had smaller tumour size." (PMID 30467960, 2019). "However, at the malignant stage, miR-323b-3p promotes the expression of TGFBR3, which acts as tumor promoters in pulmonary metastatic OS by enhancing the TGF-β signaling." (PMID 29991755, 2018). "The fusion-positive areas were the only parts of the tumor that were positive for TGFBR3." (PMID 29084941, 2017). "In addition to our focus on TGFBR3, gene-expression profiling of adjacent tumor stroma can provide information to enhance the prediction of clinical outcome in comparison to the current approaches performed in pathology." (PMID 27827906, 2016).
tumor (continued). "Treating CAFs that lack TGFBR3 with sTβRIII appears to have decreased inflammatory ability, which could potentially lead to suppression of myeloid tumor promoting cell activity." (PMID 27827906, 2016). "Further, clinical studies demonstrate that reduced levels of TGFBR3 is associated with an advanced stage in tumour cancer, a poor overall survival phenotype, and, in particular, with hormone receptor-negative and triple-negative tumours." (PMID 41463344, 2025). "Notably, accumulating evidence has demonstrated that TGFBR3 is a tumor suppressor in PC." (PMID 33280236, 2021). "TGFBR3 gene downregulation has been stated in the case of different cancers, and the observed decline in the expression of the TGFBR3 gene appears to be correlated with cancer progression, when tumor cells demonstrate an increase invasiveness and metastatic potential." (PMID 32987826, 2020). "We next tested whether TGFBR3-mediated tumor-suppressive function depends on ANG." (PMID 32471132, 2020). "However, the mutation that we suspect has the largest impact on the differential character of molecular patterns in the two tumors is the mutation in the TGFBR3 gene in the non-responder tumor." (PMID 28594404, 2017). "TGFBR3 is specifically overexpressed in MSL TNBC and has been shown to act as a tumor promoter for MSL TNBC cells." (PMID 38600165, 2024). "M2 macrophages release exosomes which contain miR-501-3p, which controls transforming growth factor beta receptor 3 (TGFBR3) mediated signaling in PDAC cells, which promotes tumor progression." (PMID 35883598, 2022). "Data on the FGF2, FGFBP1, TGFA, TGFBR3, and IGF1R expression levels were analyzed using TIMER 2.0 that matched TCGA tumor tissue with normal tissue." (PMID 36430763, 2022). "CD8-05-FGFBP2 cluster exhibited a CD8+ effector phenotype, upregulating genes involved in cytotoxicity and anti-tumor activity: FGFBP2, GNLY, FCGR3A, GZMH, PRF1, TGFBR3, and GZMB." (PMID 36350695, 2022). "TGFBR3, an essential co-receptor of the TGF-β superfamily, is involved in cancer cell migration, invasion and metastasis, and exerts tumor-suppressive roles in various cancers." (PMID 36461008, 2022). "Mechanistically, the tumor suppressor TGFBR3 is markedly reexpressed after HELLS knockdown; conversely, compromising TGFBR3 rescues HELLS knockdown‐mediated effects in PC cells." (PMID 33280236, 2021). "RNA-seq data also demonstrated that several genes related to adoptive immune systems which have pro-tumor action, such as TGFβ2, TGFBI, TGFBR1, TGFBR3, PLAU, IL-1β, and IL-33 are higher in Pn-positive cells than Pn-negative cells." (PMID 34680221, 2021). "Collectively, these data indicated that HELLS epigenetically silences the tumor suppressor TGFBR3 in PC cells, and the function of HELLS/TGFBR3 axis remains to be elucidated." (PMID 33280236, 2021). "We found an increase of TGFB1 mRNA in tumor tissues relative to healthy ones (left), and an increase of TGFB1 mRNA was inversely correlated with a decrease of TGFBR3 mRNA levels in the same patients (right)." (PMID 32471132, 2020). "In summary, we conclude that TGFBR3 is as a tumor suppressor via SMAD4-dependent and -independent manner in both tumor and stromal cells during oral carcinogenesis." (PMID 32471132, 2020). "Despite the fact that TGFBR3 is important for delivering TGF-β ligands to receptors and initiation of TGF-β signaling, this molecule is still an understudied component of the tumor microenvironment." (PMID 27827906, 2016). "Genes encoding components of the ECM, including TNXB and MATN2 were identified among downregulated transcripts, together with other participants in tumor progression, including growth factors, such as FIGF and growth factor receptors, such as TGFBR3." (PMID 21611158, 2011). "TGFBR3 may inhibit the progression of PTC by inhibiting the EMT and PI3K/AKT pathways, which play a tumor suppressor role in PTC." (PMID 39404708, 2024).
tumor (continued). "Of the gonadotroph tumours, 78.1% (n = 89) were negative for TGFBR3, 20.2% (n = 23) of tumours stained positive in 1–10% of cells and only two tumours had ≥ 10% positive staining cells." (PMID 36952069, 2023). "Considering all subtypes of NF-PitNETs, TGFBR3 staining was negative (staining score 0) in two thirds of the tumours (staining missing in 3 tumours)." (PMID 36952069, 2023). "In our study, TGFBR3 staining was absent or very low in the majority of gonadotroph tumours, although several studies have shown that TGFBR3 was expressed in gonadotroph cells of murine models suggesting an important role in gonadotropin regulation." (PMID 36952069, 2023). "Furthermore, exosomal miR-18a derived from M2 macrophages promote NPC progression, invasion, and tumor growth in in vitro and in vivo animal models via TGF-β signaling pathway by repression of transforming growth factor-beta III receptor (TGFBR3)." (PMID 35311066, 2022). "Moreover, tumor suppressor TGFBR3 was significantly reexpressed upon HELLS knockdown and served as a downstream mediator of HELLS; knockdown of TGFBR3 largely rescued HELLS knockdown‐mediated effects on PC cells." (PMID 33280236, 2021). "Vice versa, sEVs from M2-macrophages interacted with PDAC tumor cells as well as the extended TME, e.g., M2-derived sEVs with miR-501-3p inhibited transforming growth factor beta receptor 3 (TGFBR3), enabling TGF-β signaling, tumor growth, and metastasis of xenografted PDAC in nude mice." (PMID 34638330, 2021). "The size of the tumor also affected the expression of BMP3 (P = 0.0047), BMP7 (P = 0.0210), BMPR1B (P = 0.0460), ACVR2A (P = 0.0350), ACVRL1 (P = 0.0045), TGFBR2 (P = 0.0170), and TGFBR3 (P = 0.0150) according to the K-W test." (PMID 34036102, 2021). "In addition, exosomes released by macrophages promote progression of PDAC by targeting transforming growth factor beta receptor 3 (TGFBR3), a tumor suppressor gene, and activating TGF‐β signaling pathway." (PMID 34766148, 2021). "Using qPCR, we also found that TGFBR3 and HMGCS1 were downregulated in miR‐223‐OV tumor tissues." (PMID 32491253, 2020). "Finally, no relation between TGFBR3L and TGFBR3 staining was found, the latter being absent or expressed at a low level in the majority of gonadotroph tumours." (PMID 36952069, 2023). "TGFBR3 belongs to the functional process GO:0071559 (the response to transforming growth factor β) along with ACVR2B (the activin receptor type 2B) and the transcription factor ONECUT2 (one cut domain family member 2) involved, respectively, in cell signaling and tumor growth." (PMID 35740429, 2022). "Furthermore, TGFBR3 overexpression reduced buccal lymph node metastasis without affecting primary tumor growth in an animal model." (PMID 32471132, 2020). "Moreover, we identified deletions in tumor suppressors, such as DACT2 and TGFBR3." (PMID 31900418, 2020). "Interestingly, neither the primary tumor growth nor the final tumor weight were affected by TGFBR3 overexpression." (PMID 32471132, 2020). "Furthermore, SCAND1 and MZF1 expression was negatively correlated with TGFBR1, TGFBR2, and TGFBR3 gene expression, suggesting that SCAND1-MZF1 could reduce TGFβ receptors to narrow down TGFβ signals emanating from the microenvironment to tumor cells." (PMID 36552758, 2022). "The gonadotroph tumours staining for both TGFBR3L and TGFBR3 (n = 10) did not deviate from the rest of the gonadotroph cohort in regards to age, gender, staining for FSH and LH, tumour volume or cavernous sinus invasion (data not shown)." (PMID 36952069, 2023). "In conclusion, our study aimed to identify hub genes involved in HCC by WGCNA of data from the TCGA database and concluded that three functional genes (TGFBR3, COLEC10, and FYN) are highly differentially expressed in tumor and nontumor tissues." (PMID 35397600, 2022).
tumor (continued). "TGF-β type III receptor (TGFBR3) is an important part of TGF-β signal transduction, which acts as tumor suppressor in tumor and stromal cells through SMAD4-dependent and non-dependent manner during head and neck squamous cell carcinogenesis." (PMID 36090900, 2022). "Previous study also indicates that hUCMSCs home to tumor tissues but not to healthy tissues and express multiple chemokine receptors, such as SDFR1, TGFBR3, FGFR2." (PMID 27129156, 2016). "Finally, despite TGFB2 and TGFBR3 being preferentially expressed in the OC3 tumor group, in clinical samples, both genes were not significantly enriched in the tumor cell type." (PMID 32605311, 2020).
cancer (59 papers, 2010 to 2026). A tumor composed of atypical neoplastic, often pleomorphic cells that invade other tissues. "The results showed that low expression of TGFBR3 was associated with cancer-related pathways and epithelial-mesenchymal transformation (EMT) in PTC cells." (PMID 39404708, 2024). "Loss of expression of TGFBR3 correlates with disease progression and a poor prognosis, and restoration of its expression in cancer cells exerts a regulatory role in cell migration, invasion, angiogenesis and metastasis." (PMID 23387308, 2013). "Interestingly, the in vitro cell line data for cancer associated fibroblasts (CAFs) and normal-associated fibroblasts (NAFs) demonstrate a decrease of TGFBR3 in CAFs at both mRNA and protein levels." (PMID 27827906, 2016). "Moreover, decreased expression of TGFBR3 was associated with malignancy in various cancers." (PMID 37391533, 2023). "Gene signatures from our analysis reveal robust relationships between INHA, ENG, and TGFBR3 and other established cancer biomarkers." (PMID 33819300, 2021). "The alterations for the genes varied, with INHBA and TGFBR3 exhibiting higher rates of alterations (0–5.65% and 0.17–3.91% respectively) that also varied by cancer type." (PMID 33819300, 2021). "In line with this, the expression of TGFBR3 is downregulated in cancer tissues compared to the normal tissues." (PMID 32756339, 2020). "Consistent with a role in fine-tuning TGF-β1 in CAFs and endothelial cells, CM obtained from TGFBR3-overexpressing cancer cell culture exerted an inhibitory paracrine effect on the migration and invasion of CAFs, and on endothelial tube formation." (PMID 32471132, 2020). "Conversely, CM derived from TGFBR3-depleted cancer cells had cancer-promoting effects on these stromal cells." (PMID 32471132, 2020). "TAM-derived exosomes advance migration, invasion and metastasis of cancer cells in vitro and in vivo and it can be mediated by exosomal miRNA-501-3p, which certainly targets TGFBR3." (PMID 32756339, 2020). "In normal prostate epithelial cells, decreased TGFBR3 expression and/or activity results in morphological changes suggestive of inhibition of cell–cell contacts and stimulation of the cancer stem cell phenotype." (PMID 31842336, 2019). "Further experiments that investigate how tumors and their genetic alterations influence TGFBR3 will be useful in many types of cancers." (PMID 27827906, 2016). "Statistically significant associations, corrected for multiple testing, were observed for the transcripts TBX21 and TGFBR3, which are mediators of the immune system, and LGR6 and STX16 that have been repeatedly associated with cancer progression." (PMID 24194869, 2013). "A growing body of studies have shown that TGFBR3 is lost in a variety of cancers, including human kidney, pancreas, prostate, lung, breast and ovary carcinomas." (PMID 23387308, 2013). "Additionally, TGFBR3 (also known as Betaglycan) is involved in cancer progression and has been suggested as a prognostic marker for cancer metastasis." (PMID 41256734, 2025). "TGFBR3 is a locus that encodes the transforming growth factor (TGF)-beta type III receptor, which can regulate cell apoptosis, and is widely known as a cancer control factor." (PMID 35783123, 2022). "Reduced expression of the TGFBR3 protein has also been observed in various other cancers." (PMID 34767591, 2021). "Both ENG and TGFBR3 were predictive in other cancer types as well." (PMID 33819300, 2021). "TGFBR3 expression level has been reported to be decreased in a wide variety of cancers." (PMID 33002292, 2020). "We sought to dissect whether ARRB2 or GIPC1 plays a role in TGFBR3-dependent cancer-suppressive activity." (PMID 32471132, 2020).
cancer (continued). "Our results showed a higher expression in the cancer when compared with its counterpart, which indicates that this miRNA might be related to TGFBR3." (PMID 33182525, 2020). "While carcinomas resulted in variable changes to the HSPGs, TGFBR3 was notably decreased." (PMID 32992731, 2020). "TF ZEB1, which is an important regulator of EMT during embryonic development and cancer progression, is modified by phosphorylation to increase its transcriptional activity to downregulate the expression of TGFBR3 and integrate cytokines and growth factors in the local environment of cancer cells." (PMID 31126066, 2019). "In addition, TGF beta was shown to be associated with the cell-surface chondroitin sulfate/heparan sulfate proteoglycan betaglycan (also referred to as transforming growth factor beta receptor III, TGFBR3) on the surface of cancer cell-derived exosomes." (PMID 29663027, 2018). "Similarly, the expression of the type II receptor (TGFBR2) and type III receptor (TGFBR3) were upregulated by the cancer cells in co-culture." (PMID 27819283, 2016). "TGFBR3 may be as a mediator of cancer progression and epithelial to mesenchymal transition factor." (PMID 32189110, 2020). "TF ZEB1 could positively regulate target gene TGFBR3 to promote cancer cell EMT and migration." (PMID 31126066, 2019). "TGFBR3 overexpression alone exerts a strong inhibitory effect on migration and EMT of CAL-27 tongue squamous cancer cells, while overexpression of miR-19a and miR-424 downregulates TGFBR3 and triggers EMT and cancer cell migration." (PMID 36358747, 2022). "Clustering analysis for genes correlated with INHA, TGFBR3, or ENG in cancers revealed ENG and TGFBR3 had very few genes correlated exclusively to one or the other." (PMID 33819300, 2021). "TGFBR3 downregulation is the most common modification of the TGF-β signaling pathway in prostate cancer and contributes to stimulation of cancer cells’ motility and invasiveness in vitro as well as enhanced tumorigenicity in vivo." (PMID 31842336, 2019). "These include some known cancer biomarkers such as PCGs CDK1 and TGFBR3, as well lncRNAs PVT1 and ADAMTS9-AS2." (PMID 26812883, 2016). "TGFBR3, SnoN, and GRHL2 have also been shown to play dual roles in different types of cancer." (PMID 35765957, 2022). "Indeed, overexpression of TGFBR3 can reverse the effects of TAM-derived exosomes and miRNA-501-3p on cancer cells." (PMID 32756339, 2020). "There are few reports about the role of TGFBR3 and HMGCS1, especially HMGCS1 in cancer progression." (PMID 32491253, 2020). "Consistently, our study revealed that the TGF-β signaling pathway was implicated in the effect of miR-501-3p-mediated downregulation of TGFBR3 on PDAC cells, which indicated a conserved anti-oncogenic role of TGFBR3 in combination with results in other cancers." (PMID 31307515, 2019). "Interestingly, transmembrane proteins and proteins coupled to receptor activity, such as the cancer-related EGFR and TGFBR3, were also tightly regulated." (PMID 30958262, 2019). "Moreover, INHA itself was dependent on TGFBR3 and ENG/CD105 in multiple cancer types." (PMID 33819300, 2021). "Furthermore, other secreted TGFBR3-regulated molecules not included in the array may promote CM’s anti-cancer activity." (PMID 32471132, 2020). "CFP1 upregulated expression of β-catenin, LEF1, TCF1/TCF7, c-MYC, TGFBR3, and TGFB1, and the cancer-promoting effects of CFP1 were not completely repressed by pathway inhibitors." (PMID 37735441, 2023).